MMP3 (matrix metallopeptidase 3)
Diseases named in the same sentence as MMP3 in open-access papers (continued):
Sharing a sentence is not in itself a finding about the gene and the disease.
breast cancer (continued). "In the present study SNPs of MMP1, MMP3 and MMP9 genes were correlated with clinicopathological features for their association in breast cancer progression and susceptibility." (PMID 28961241, 2017). "In conclusion, our results suggest that MMP1–1607 1G/2G, MMP3–1171 5A/6A and MMP9–1562 C/T gene polymorphisms have strong correlation with breast cancer." (PMID 28961241, 2017). "Genotype and allele frequencies distribution for MMP-1, MMP-3 and MMP-9 gene polymorphisms in controls and breast cancer subjects." (PMID 28961241, 2017). "Particularly, MMP3 has been shown to drive the formation of mammary tumors in mice when over-expressed in mammary epithelial cells." (PMID 28143606, 2017). "Our results suggest that MMP1–1607 1G/2G, MMP3–1171 5A/6A and MMP9–1562 C/T gene polymorphisms have synergistic effect on breast cancer." (PMID 28961241, 2017). "In support of disease specific effects of MMP-s, MMP-3 is known to promote breast cancer progression but protect against the progression of squamous cell carcinoma." (PMID 28241871, 2017). "Several MMPs have been reported to induce EMT, including MMP-3 in breast cancer, MMP-7 in gastric and lung cancer cell lines, MMP-9 in ovarian and squamous cancer cell lines, and MT1-MMP in an ischemic rat kidney cell line." (PMID 27374080, 2016). "To further assess the possible relationship between MT3 overexpression and down-regulation of MMP3, we created a specific loss-of-function phenotype using siRNAs in order to inhibit the expression of MT3 in breast cancer MDA-MB-231 cells." (PMID 25933064, 2015). "Using in vitro matrigel invasion assay, a statistically significant decrease in invasiveness was found in the case of breast cancer cells with MMP3 expression silenced, in comparison to the control cells." (PMID 25933064, 2015). "Matrix metalloproteinase-3 (MMP-3) and parathyroid hormone-like hormone (Pthlh) genes encode secreted factors implicated previously in breast cancer progression." (PMID 25633981, 2015). "Transgenic mice overexpressing MMP-3 in their mammary glands show reduced carcinogen-induced mammary tumors as a result of increased epithelial cell apoptosis." (PMID 25848906, 2015). "In summary, we have shown that overexpression of MT3 in breast cancer cells increases their invasiveness, most probably via upregulation of MMP3 activity." (PMID 25933064, 2015). "Recently, several investigations have shown that Gpnmb accelerates the motility of hepatoma cells and promotes breast cancer metastasis to bone by inducing MMP-3 expression." (PMID 26599547, 2015). "Gpnmb enhanced MMP-3 expression in 4TI-mouse mammary carcinoma cells, suggesting the role of Gpnmb in tumor aggressiveness." (PMID 26581806, 2015). "We also found our dataset of MMP-3-induced transcriptional responses to overlap with transcriptional profiles of higher grade and more aggressive breast cancer subtypes." (PMID 24811539, 2014). "We also show that MMP-3/Rac1b-induced EMT activates transcriptional alterations characteristic of poor prognosis human breast cancer subtypes." (PMID 24811539, 2014). "MMP3 and MMP9 were associated with breast cancer risk among those with most Native American ancestry and those with ER−/PR− tumors." (PMID 23696797, 2013). "We found that MMP-3 was partially involved in astrocyte CM-induced breast cancer cell invasion but to a lesser extent compared with either MMP-2 or MMP-9." (PMID 24324647, 2013). "MMP-3 has also been shown to facilitate breast cancer metastasis to the brain, which was blocked by MMP inhibition." (PMID 23840733, 2013). "In this sense, high levels of MMP2, MMP3 and MMP9 proteins have been implicated in several malignancies including oesophageal, renal, head and neck, oral, colorectal, NSCLC, breast carcinomas and melanomas." (PMID 22455335, 2012). "Several MMPs have been implicated as having a role in breast cancer, including MMP-1, MMP-2, MMP-3, and MMP-9, among others." (PMID 17922906, 2007).
breast cancer (continued). "We utilised the unique in situ-reverse transcription-polymerase chain reaction (IS-RT-PCR) methodology to localise the in vitro and in vivo gene expression of MT1-MMP, MMP-1 and MMP-3 in human breast cancer." (PMID 16430785, 2006). "Elevated expression of MMP-3, 7, 8, 9, 11, 12, 13, 14, 23B, 26 and 28 in AA breast cancer cells was observed when the overall averages of the expression levels of all AA and CAU women cell lines were compared." (PMID 15511301, 2004). "MMP3 has been implicated in promoting EMT through various mechanisms, including Rac1b-mediated reactive oxygen species (ROS) production, which enhances malignancy in breast cancer." (PMID 41583390, 2026). "Interestingly, MDH2 overexpression upregulated several genes associated with breast cancer metastasis (IL13RA2, MMP3, PTGS1, SYK, VCAN, and FLT1) and downregulated several genes associated with metastasis suppression (NOTCH3 and HTRA3)." (PMID 41179294, 2025). "The aberrant expression of matrix metalloproteinase-3 (MMP-3) and tissue inhibitor of metalloproteinase-3 (TIMP-3) is potentially associated with metastasis in several carcinomas such as NPC, cervical cancer, breast cancer, lung cancer, and colon cancer." (PMID 37037466, 2023). "Additionally, there is an article that investigates the potential of circulating MMP3 as a prognostic marker for breast cancer, where elevated serum levels of MMP3 were reported in breast cancer patients." (PMID 37048701, 2023). "Matrix metallopeptidase 3 (MMP3) is one of the most studied MMP enzymes, and its overexpression has been associated with tumor growth and invasion in various types of tumors, including breast cancer, prostate cancer, pancreatic cancer, and gliomas." (PMID 37834154, 2023). "Importantly, MMP3 is currently being investigated as a novel protein target for treatment of lung and breast cancer, highlighting potential opportunities for drug-repurposing for IHD." (PMID 37940228, 2023). "In addition, they discovered a correlation between MMP3 and the prognosis of breast cancer patients." (PMID 37940644, 2023). "Several changes are induced by MMP-3 (increased cell proliferation, apoptosis, angiogenesis, changes in the stroma, etc.), which may result in the development of breast cancer in women." (PMID 37999477, 2023). "Moreover, the upregulation of matrix metallopeptidase 3 (MMP3) has been associated with cancer metastasis and tumor growth in breast cancer." (PMID 35008958, 2022). "Moreover, in another study, loss of stromal MMP-3 was found to increase the tumor burden, suggesting that stromal MMP-3 plays a protective role during breast cancer development by inhibiting tumor growth." (PMID 36741729, 2022). "Interestingly, primary tumor expressing ANGPTL7, MMP3, LCN2, S100A8, and ESM-1 levels that were upregulated in 4T1.2 cells was strongly associated with breast cancer patients’ survival outcomes." (PMID 34072157, 2021). "The overexpression of MMP-3 had been shown to drive the formation of mammary tumors in mice." (PMID 34527741, 2021). "MMP-1 and MMP-3 are involved in the maintenance of the angiogenic phenotype; thus, inhibition of these proteinases may be of value both in preventing breast cancer and in blocking metastasis of established tumors." (PMID 34445715, 2021). "For this, the production of MMP3, which might be involved in metastatic dissemination of breast cancer, was evaluated." (PMID 32699527, 2020). "In addition, MMP3 expression in the murine model of mammary carcinoma has been demonstrated to be important for primary tumor and metastasis growth." (PMID 32854182, 2020). "The aim of the study was to evaluate if plasma levels of selected metalloproteinases (MMPs) (stromelysin-1 (MMP-3) and stromelysin-10 (MMP-10)) and cancer antigen 15-3 (CA 15-3) used separately and in combination demonstrated diagnostic usefulness in breast cancer (BC)." (PMID 33371324, 2020).
breast cancer (continued). "Interestingly, in the trabecular or cortical bone of tumor-bearing mice injected with MDA-MB-231GFP/Luc2 cells injected alone, MMP3 expression was observed near or adjacent to GFP breast cancer cells (~ 17% of cells)." (PMID 30813947, 2019). "In addition to an upregulation of transcription factors, we found an increased expression of IL1RN and the matrix metalloproteinases MMP2 and MMP3 in PRAME overexpressing breast cancer cells." (PMID 30602372, 2019). "The matrix remodeling protease gelatinase-B (Mmp9) is associated with breast cancer risk, and Mmp9, but not Mmp3, was elevated in glands from R72 mice." (PMID 30651598, 2019). "In contrast, RAC1B protein along with MMP3 proteins was reported to be both strongly expressed by breast tumor cells and MMP3 gene expression can serve as a prognostic marker for patient survival in breast cancer." (PMID 30621237, 2019). "MMP3 is expressed in higher levels breast cancer and involved in mammary carcinogenesis." (PMID 30237863, 2018). "However, MMP-3 also inhibits tumor progression in breast cancer and skin squamous cell carcinoma, studies have reported increased tumor growth rates and higher proliferative indices in MMP-3-null mice." (PMID 29390034, 2018). "Also, we show that IL1B-mediated breast cancer cell invasion, and the induction of MMP3 and IL1B itself, occurs in an OPG-dependent manner." (PMID 28143606, 2017). "Treatment with cmvIL-10 also increased expression of both urokinase plasminogen receptor (uPAR) and plasminogen activator inhibitor-1 (PAI-1), which can stimulate MMP-3 activity and have previously been identified as poor prognostic markers in breast cancer patients." (PMID 28228690, 2017). "Overall, our results revealed that the polymorphisms in the promoter region of MMP1, MMP3 and MMP9 when correlated with clinicopathological characteristics and survival rate have shown significant effects on the risk and progression of breast cancer, substantiated by in-silico analysis." (PMID 28961241, 2017). "We therefore asked whether OPG was important in IL1B-mediated MMP3 induction in breast cancer cells." (PMID 28143606, 2017). "Our data suggest that MT3 may regulate breast cancer cell invasiveness by modulating the expression of MMP3." (PMID 25933064, 2015). "Importantly, the cell type of origin has been found previously to be a significant factor modulating prognostic interpretation for a number of MMPs in breast cancer, including MMP3 specifically." (PMID 26807201, 2015). "Here, we used profiling methods to identify MMP-3-induced transcriptional alterations in mouse mammary epithelial cells, finding common overlap with changes mediated by nuclear factor-κB (NF-κB) and found in advanced breast cancer." (PMID 24811539, 2014). "Significantly, in the present study we found overlap of the geneset induced by MMP-3/ROS signaling in mammary epithelial cells with multiple datasets from other studies comparing the basal intrinsic subtype of breast cancer with other, less aggressive, subtypes." (PMID 24811539, 2014). "One study showed that transfection of MMP-3 gene into breast cancer cells could induce both hydrogen peroxide and Snail." (PMID 24617993, 2014). "MMPs, specifically MMP-3, have been shown to promote mammary tumor progression." (PMID 23840733, 2013). "When stratifying by percent Native American ancestry, MMP3 and MMP9 were associated with breast cancer risk among women with more Native American ancestry only; the p for interaction with MMP9 remained statistically significant after adjustment for multiple comparisons (padj = 0.002)." (PMID 23696797, 2013). "Another study reported decreased development of mammary tumors in transgenic mice expressing MMP3." (PMID 21170377, 2010). "Some studies documented the expression of MMP-3 in breast cancer." (PMID 19531263, 2009).
breast cancer (continued). "Furthermore, selective antagonists for MMP-2/MMP-9 or MMP-3 also suppressed the stimulatory effect of IL-17 on breast cancer invasion, although to a lesser extent than GM6001." (PMID 19014637, 2008). "Evidence for a role for MMP-3 in breast cancer comes from tissue studies and animal models." (PMID 17922906, 2007). "The results do suggest that, in women with breast cancer, a high-expressing MMP-3 genotype may promote tumor progression more effectively." (PMID 17922906, 2007). "Some have reported an increased risk for breast cancer in women carrying the MMP-3 5A allele, but this has not been confirmed in other studies." (PMID 17922906, 2007). "Using a large cohort of patients with breast cancer, Krippl and colleagues demonstrated that the MMP-3 promoter polymorphism did not influence disease susceptibility." (PMID 17311017, 2007). "In conclusion, our results suggest that dissimilarly expression of few mediator encoding genes ANPTl7, MMP3, S100A8, LCN2 ESM1 in primary versus distant metastasis organs and their prognostic and predictive scores in breast cancer cohort may be a helpful to predict future metastasis." (PMID 34072157, 2021). "Moreover, a study in melanoma and breast cancer mouse models showed that ANG2 along with matrix metalloproteinase 3 (MMP3) and MMP10 are upregulated in the pulmonary premetastatic niche and are associated with impaired vascular integrity and increased tumor cell extravasation." (PMID 33217955, 2020). "In support of this, MMP3 overexpressing transgenic mice developed spontaneous pre-malignant lesions and mammary cancers despite the lack of carcinogens or pre-existing gene mutations, indicating that abnormal MMP3 activity is sufficient to initiate cancer cell transformation." (PMID 26956475, 2016). "Integrated molecular analysis of these tumours revealed important genes – including those that encode matrix metalloproteinase-3 (MMP-3) and parathyroid hormone-like hormone (Pthlh) – whose dysregulation might be causally involved in metastatic dissemination of breast cancer." (PMID 25633981, 2015). "We evaluated genetic variation in MMP1 (9 SNPs), MMP2 (8 SNPs), MMP3 (4 SNPs), and MMP9 (3 SNPs) and breast cancer risk among Hispanic (2111 cases, 2597 controls) and non-Hispanic white (NHW) (1481 cases, 1586 controls) women in the Breast Cancer Health Disparities Study." (PMID 23696797, 2013). "As MT1-MMP, MMP-1 and MMP-3 have all been implicated in the processes involved in human breast cancer, this study utilised HBC cell lines both in culture and grown as xenografts in nude mice, to investigate gene expression changes of MT1-MMP, MMP-1 and MMP-3 in vitro and in vivo using IS-RT-PCR." (PMID 16430785, 2006). "Specifically, we observed up-regulation of genes that drive breast cancer metastasis (IL13RA2, MMP3, PTGS1, SYK, VCAN, and FLT1) and downregulation of metastasis-associated suppressor genes (NOTCH3, and HTRA3)." (PMID 41179294, 2025). "We found that COL1A1, MMP3, PDGFR and FZD7 were significantly increased/decreased in breast cancer brain metastasis compared with primary breast cancer, and the four genes were also acted as long-term outcome factors in breast cancer brain metastasis." (PMID 39157383, 2024). "In breast cancer (BC), overexpressing ECM1 increases matrix metalloproteinase 3 (MMP3) and S100A/B protein levels." (PMID 38402239, 2024). "Expression levels of ECM degrading proteases MMP2, MMP3, and MMP14 significantly increased in lung fibroblasts exposed to media conditioned by metastatic breast cancer cells as compared to controls." (PMID 37903851, 2023). "The upregulation of PODXL, MMP3 and MMP9 are believed to promote cell migration 48-50, suggesting CREB activation is critical for GPT2/GABA-induced breast cancer migration." (PMID 36923530, 2023). "For instance, MMP3-mediated cleavage of IGF-BP3 and IGF-BP5 inhibits tumorigenesis in breast cancer." (PMID 37024866, 2023).
breast cancer (continued). "Meanwhile, exogenous miR-186-5p mimic in MDA-MB-231 cells significantly inhibited the expression of SBEM, p-PI3K, p-AKT and their downstream pathways, MMP1, MMP3, MMP9, CyclinD1, PCNA and CyclinB1 proteins and reduced proliferation of breast cancer cells." (PMID 37477531, 2023). "The activated transcription factor CREB accelerates breast cancer metastasis by upregulating metastasis-related gene expressions, such as PODXL, MMP3, and MMP9." (PMID 36923530, 2023). "It is worth noting, however, that in our team’s previous work, we observed an increase in plasma MMP-3 and MMP-7 concentrations in stage III–IV breast cancer patients when compared to patients who were found to be at stage I." (PMID 37048701, 2023). "For example, in breast cancer (BC), PNU-74654 can inhibit cell migration and invasion by upregulating E-cadherin and downregulating MMP3 and MMP9, thereby providing a synergistic enhancement of the anticancer effect of fluorouracil (5-FU)." (PMID 37763649, 2023). "MMP3, also known as stromelysin-1, degrades several ECM components, such as collagens, laminins, and fibronectin, and has been known to exert oncogenic effects in prostate and breast cancers." (PMID 35439171, 2022). "Particularly, MMP-3 and 7 have been shown to promote EMT in breast cancer cells in vitro through direct cleavage of E-cadherin." (PMID 35008415, 2022). "Macrophage-CM also increased MMP-3 and MMP-11 expression by adipocytes in adipocyte–breast cancer co-culture." (PMID 36551185, 2022). "Our data suggested that tRF-17-79MP9PP inhibits the THBS1-mediated TGF-β1/Smad3 pathway and the EMT related genes (MMP3, MMP-9 and N-cadherin) in breast cancer cells." (PMID 33912465, 2021). "In breast cancer, ARPC2 expression significantly upregulated the expression of vimentin, N-cadherin, MMP-9, ZEB1, and MMP-3, activated the TGF-β pathway, and eventually led to epithelial–mesenchymal transition (EMT)." (PMID 34307456, 2021). "LOX, MMP2, MMP3, MMP9, RHOA, VIM gene panel expression monitoring was considered because they are correlated with a more aggressive and invasive phenotype in breast cancer cells." (PMID 33543395, 2021). "Our previous work has shown the involvement of MMP-3, MMP-9, TIMP-3, and TIMP-4 in response to radiotherapy in breast cancer patients, suggesting their utility as potential prognostic and predictive biomarkers for this pathology." (PMID 34445715, 2021). "Overexpressing LPP1 also decreased mRNA levels of MMP-1, MMP-3 and MMP-13 in BT-549 breast cancer cells and 4T1 mouse breast cancer cells." (PMID 31534541, 2019). "Evidence have shown that CXCR4 drives the metastatic phenotype in breast cancer through induction of CXCR2 and activation of MEK and PI3K pathways, while MMP3 contributes to the precision of epithelial cell branching via the processing of ECM components." (PMID 31798768, 2019). "The present study mainly focused on the analysis of synergistic effects of three functional SNPs of MMP1 (rs1799750) -1607 1G/2G, MMP3 (rs35068180) -1171 5A/6A and MMP9 (rs3918242) -1562 C/T genes in relation to breast cancer development and progression." (PMID 28961241, 2017). "Direct interdependence between the increased expression of MMP3 and overexpression of MT3 was further confirmed by transfecting human breast cancer MDA-MB-231 cells with siRNA to silence the expression of MT3." (PMID 25933064, 2015). "We found that MMP-3 expression, which is regulated by PELP1 in MDA-231 breast cancer cells, was upregulated in PELP1-cyto HMECs." (PMID 25789479, 2015). "To the best of our knowledge, we showed for the first time that suppression of integrin ανβ6 in MCF-7 human breast carcinoma cells dramatically reduced pro-MMP-9, pro-MMP-3 and uPA secretion in tumor conditioned medium." (PMID 25176506, 2014).